CD44 (CD44 molecule (IN blood group))
Diseases named in the same sentence as CD44 in open-access papers (continued):
Sharing a sentence is not in itself a finding about the gene and the disease.
colorectal cancer (continued). "CircFMN2/miR-1182 may also regulate the progression of colorectal cancer by targeting CD44, GNG7, RB1, COL1A2, PLCB1, SLC17A7, and TERT." (PMID 34249673, 2021). "CD44+ colon cancer stem cells (CCSCs) were isolated from mouse colorectal carcinoma CT-26 cell cultures and induced to form defective ribosomal products-containing autophagosome-rich blebs (DRibbles) by treatment with rapamycin, bortezomib, and ammonium chloride." (PMID 34400894, 2021). "Besides, numerous studies suggest that CD44 can be a promising predictor for clinical outcomes among cancer population, including gastric cancer, colorectal cancer, neuroblastoma, myxofibrosarcoma, glioma, endometrial cancer and osteosarcoma." (PMID 33303029, 2020). "However, CD44 epithelial isoform has been found to be negatively correlated with lymphatic invasion and metastasis of colorectal cancer based on the statistical analysis of a total of 494 colorectal tumor samples." (PMID 33303029, 2020). "Also interestingly, the 3’UTR of PLAGL2 was found to be independently overexpressed in colorectal cancer cells, and has an independent function in regulating C-Myc and CD44 expression and in promoting cell proliferation and tumor growth." (PMID 32087738, 2020). "Brachyury, a member of the T-box gene family, induces stemness markers such as NANOG, CD133, CD166, and CD44 in a colorectal cancer cell line by regulating the β-catenin oncogene and contributing to the epithelial-to-mesenchymal transition (EMT) that mediates invasion by tumor cells and metastasis." (PMID 33447348, 2020). "In both breast and colorectal cancer, CD44 and BRCA2 showed a strong positive correlation." (PMID 32610620, 2020). "Thus, we are hopeful that anti-CD44 therapy will be applied in the treatment of colorectal cancer in the future." (PMID 30631039, 2019). "The CD44 splice variants are differentially expressed in both the normal and cancer cells, e.g., CD44v8-10 in pancreatic cancers and CD44v6 in colorectal cancer including CSCs, which is a useful marker of tumor prognosis." (PMID 31013960, 2019). "HGF expression in CC-CAFs was higher that of normal fibroblasts, CC-CAFs promote metastasis of colorectal cancer through HGF/c-Met which induce up-regulation of CD44 whose correlation with metastasis can be observed in clinical specimen and orthotopic liver metastatic model." (PMID 31367190, 2019). "Ternary nanocomplexes of HA conjugates with poly(hexamethylene biguanide) and chitosan were to deliver an anti-KRAS siRNA to colorectal cancer cells, exploiting the interaction of HA with CD44 as a means to achieve selective targeting of CD44-positive cancer cells." (PMID 31627389, 2019). "To test whether combination treatments of resveratrol and 5-FU abolish CD44 expressions, we treated the colorectal cancer cell lines with mono- and combo-therapies of resveratrol and 5-FU, then performed western blot analysis." (PMID 30250641, 2018). "Patients having colorectal cancer with high expression of CD44 exon 6 had a poor prognosis." (PMID 29356399, 2018). "Importantly, knocking down ID2 expression reduced CD44 expression and tumor-sphere formation and reduced the metastatic potential of colorectal cancer cells in vivo." (PMID 29652830, 2018). "In colorectal cancer, the expression of CD44 is enhanced both in adenomas and in carcinomas." (PMID 29652830, 2018).
colorectal cancer (continued). "To validate the effects of JIB-04 on the mRNA expression of β-catenin target genes, we measured the mRNA levels of CSC-associated genes (CD44, LGR5, DKK1, ALDH1A3, ALDH1B1, CD24, and SOX4) by qRT-PCR in three different colorectal cancer cell lines after treament with JIB-04." (PMID 29700375, 2018). "For example, CD44v6, an alternative CD44 splicing variant containing exon v6, showed markedly increased levels at the late or metastatic stage of gastric and colorectal cancers, but this CD44 isoform exhibited dramatic reduction in head and neck squamous cell carcinoma." (PMID 28257090, 2017). "CD133 and CD44 are well-recognized stem cell biomarkers expressed in colorectal cancer." (PMID 26840024, 2016). "Indeed, treating the colorectal-cancer cells with the Wnt/β-catenin-signaling inhibitor for 48 h decreased the size of the CD44+ subpopulation." (PMID 26965643, 2016). "Targeting CD44+ and CD133+ cancer cells involving a CD133+CD44+ cell subpopulation might be a way for colorectal cancer therapy." (PMID 27564296, 2016). "Cancer-associated fibroblasts from B16 melanoma tumors were found to express high levels of CD44, and co-culture of human colorectal cancer HT29 cells and human lung carcinoma LLC1 cells with these fibroblasts resulted in drug resistance, tumor sphere formation, and tumor growth." (PMID 25954275, 2015). "CD44 acts as a cell adhesion molecule and is involved in the regulation of the malignant biological behavior of tumor cells and promotes the growth and metastasis of many types of cancer, including ovarian, breast and colorectal cancer." (PMID 25658794, 2015). "Importantly, CD44 has been identified as a biomarker of CSCs, which have the properties of self-renewal, clonal formation, and tumorigenesis in vivo, such as in colorectal cancer and prostate cancer." (PMID 26202311, 2015). "The function of CD44 in colorectal cancer might be due to its role as a modulator of Wnt signaling or as a Wnt-target gene since one partner of CD44v6, namely the Met RTK, is also over-expressed in colorectal cancer." (PMID 25904917, 2015). "CD133 has also been used as a marker for colorectal carcinoma stem cells, whereas other studies demonstrated that such cells could be identified by expression of either EpCAM or CD44 or a combination of EpCAM, CD44 and CD166 or ALDH1." (PMID 26703575, 2015). "Thus, the results of this study indicate that EpCAMhigh/CD44+, a marker of colorectal cancer stem cells, is significantly correlated with the invasion and metastases of colorectal cancer." (PMID 24765173, 2014). "However, in colorectal cancer tissue and their corresponding liver metastases, EpCAMhigh/CD44+ cells were visible." (PMID 24765173, 2014). "EpCAMhigh/CD44+, which is regarded as a marker of colorectal cancer stem cells, is significantly correlated with the invasion and metastasis of colorectal cancer, suggesting that this molecular marker may promote the progression of tumors." (PMID 24765173, 2014). "However, in samples of colorectal cancer and their corresponding liver metastases, EpCAMhigh/CD44+ cells were visible." (PMID 24765173, 2014). "In colorectal cancer, the clonal expansion and xenograft initiation capacity of CD44+ CSCs could be inhibited by CD44 knockdown." (PMID 23349823, 2013). "Hence, CD44 is extensively used as a surface marker for isolating CSCs from breast, prostate, pancreas, ovarian, and colorectal cancers." (PMID 22693526, 2012). "However, recent studies on colorectal cancer cell lines demonstrated that CD44+/CD24+ cells showed greater clonogenic ability in vitro and tumour initiation in vivo." (PMID 22693526, 2012). "Since the CD44+ and CD166+ cells are also considered as the TICs in colorectal cancer, we also asked whether these markers were associated with CD133 and affected by hypoxia and serum depletion." (PMID 23185379, 2012).
colorectal cancer (continued). "Several studies have reported several transient molecular alterations which occur during tumor budding and experimental analyses have demonstrated interactions between cellular adhesion molecules, including β-catenin, E-cadherin, CD44 and laminin-5γ2, and tumor budding in colorectal carcinoma." (PMID 22940760, 2012). "Furthermore, the Wnt target gene CD44 has been identified as a marker for colorectal cancer stem cells, and deletion of CD44 in APCMin/+ mice attenuates intestinal tumorigenesis." (PMID 24212796, 2011). "For example, the clonal expansion and xenograft initiation capacity of CD44+-selected colorectal cancer CSC could be inhibited by CD44 knockdown." (PMID 21124918, 2010). "Furthermore, CD44 expression is, directly or indirectly, regulated by the β-catenin/Tcf-4 signaling pathway, especially in the colorectal cancer precursor lesions, suggesting a role for CD44 in intestinal tumorigenesis." (PMID 20696077, 2010). "Therefore, the basolateral expression of CD44 may serve as an adhesion-mediated signal transduction, which contributes to colorectal cancer tumorigenesis." (PMID 41009730, 2025). "Additional studies found a CD44-HA role in the interaction between colorectal carcinoma (CRC)-derived EVs and monocytes." (PMID 39851567, 2025). "Moreover, considering the CD44 selectivity of HA, NGR-conjugated HA complexes may be potent tools in targeting CD44-positive malignancies, including breast and colorectal cancers." (PMID 37760428, 2023). "In addition, we also found that miR-6511b-5p can directly target brahma-related gene 1 (BRG1), also known as SMARCA4, a key regulator of CD44 and a major transcriptional regulator, to suppress invasion and migration by regulating CD44 in pMMR colorectal cancer cells." (PMID 35590122, 2022). "Furthermore, we examined the mechanisms of invasion and migration regulated by miR-6511b-5p and determined whether miR-6511b-5p abated the invasion and migration ability of pMMR colorectal cancer cells by inhibiting CD44." (PMID 35590122, 2022). "However, whether BRG1 is directly targeted by miR-6511b-5p and increases the transcriptional activity of CD44 to promote the invasion and migration of colorectal cancer cells remains unclear." (PMID 35590122, 2022). "Thus, we explored whether CD44 is a potential downstream gene of miR-6511b-5p in colorectal cancer metastasis." (PMID 35590122, 2022). "However, the detailed mechanism by which BRG1 modulates CD44 expression in colorectal cancer remains unknown." (PMID 35590122, 2022). "Therefore, in this research, CD133+/CD44+ colorectal cancer stem cells were sorted and collected." (PMID 35470736, 2022). "Moreover, we demonstrated that the loss of BRG-1 correlates with a lack of CD44 expression by influencing the methylation of the CD44 promoter in colorectal cancer cell lines, which could be restored in the presence of 5-aza." (PMID 35590122, 2022). "Furthermore, the expression of three colorectal cancer stem cell markers, CD44, CD66c and CD133, were evaluated on CD326+ and CD26+/CD326− cells, observing the consistent expression of CD44 and CD66c along with a substantial negativity for CD133 (data not shown)." (PMID 25624884, 2015). "Hence, CD133 and CD44 have both been reported as markers of CSCs in colorectal cancer." (PMID 24960044, 2014). "This suggests that EpCAMhigh/CD44+ may be used as a marker of colorectal cancer stem cells." (PMID 24765173, 2014).
colorectal cancer (continued). "Additionally, claudin-7 has been shown to complex with a CD44 in colorectal cancer cells." (PMID 23521713, 2013). "CD44 could be one of the key molecules through which CO-029 promotes cell motility and cancer metastasis, especially given that CO-029 and CD44 form a complex in colorectal cancer cells and correlate with the progression of this cancer." (PMID 22679508, 2012). "Therefore, we investigated whether the lung and colorectal carcinoma cells used in this study express additional tumour stem cell markers such as CD44 and CD133, as we showed that they expressed EpCAM." (PMID 19002182, 2008). "Firstly, we assessed the expression of HA and its main receptor, CD44, alongside BRCA1 and 2 to explore potential relationships in breast and colorectal cancer tissues." (PMID 41373491, 2025). "For instance, miR-302c-3p targets TIM4 in cervical cancer, miR-144 targets MUC2 in colorectal cancer, miR-706 and miR-665 target ASGR2 and CD44 in gastric cancer, and miR-532-3p and miR-593-5p target MAPK genes in lung cancer." (PMID 41378310, 2025). "The results showed that in the CT26 colorectal cancer model, the DAC and 5-FU treatments significantly downregulated the expression of PD-1 and the MFI value in CD44+CD8+ TILs compared with the PBS control." (PMID 40236705, 2025). "Phenethyl isothiocyanate showed promising results on colorectal cancer stem cells (in vitro and in vivo) by decreasing the expression of stemness markers (Nanog, Oct4, Sox2, ALDH1, CD44, EpCAM), inhibiting EMT, and down-regulating ERK and phosphor-Smad2/3." (PMID 39859345, 2025). "Genistein was found to inhibit the growth of colorectal cancer stem cells in an animal model of carcinogenesis induced with dimethyl hydrazine, through the down-regulation of CD133/CD44 and the inhibition of the Wnt/β-catenin signaling pathway." (PMID 39859345, 2025). "Research has indicated that musarin significantly inhibits the proliferation of different colorectal cancer cells in a dose-dependent manner, and it particularly inhibits the proliferation of CD24+ CD44+ HT29 cells with CSC characteristics." (PMID 40507156, 2025). "We meticulously analyzed the intricate regulatory network inside the TME of colorectal cancer, namely the immune signaling interactions between tumor cells and macrophages via the MIF-(CD74+CD44) signaling pathway." (PMID 40842994, 2025). "HA and CD44, the main HA receptor, levels were evaluated in tumor tissue (TT) and non-tumor tissue adjacent to the tumors (NAT) of both breast and colorectal cancer patients." (PMID 41373491, 2025). "Compared with CD44+ stem cells or CD133+ stem cells, the proportion of ALDH+ cells in colorectal cancer is quite low, while cells with stronger tumor‐initiating properties can be selected through isolation by combining these markers together." (PMID 41346572, 2025). "They found that silencing or ablation of CD44 can promote mitochondrial OXPHOS in breast and colorectal cancer cells." (PMID 39979265, 2025). "Functionalization with hyaluronic acid (HA) was employed to target CD44-overexpressing cancer cells, specifically triple-negative breast cancer (MDA-MB-231) and colorectal cancer cell lines (HCT 116)." (PMID 41002533, 2025). "The effects of CD44 on colorectal cancer (CRC) and macrophage polarization were investigated by knocking down the expression of CD44 in HCT-116 cell and macrophages in vitro." (PMID 38590654, 2024). "CD44 is crucial for maintaining the CSC phenotype and for supporting cancer cell expansion in both in vitro and in vivo colorectal cancer cell studies." (PMID 38391955, 2024). "CT26 HA is a kind of expression of colon cancer cells, CD44 and TLR4 CRISPR knockout CT26 colorectal cancer cell was relatively slow growth, this suggests the HA combination of CD44 and TLR4 promote CT26 homologous grafts of tumor growth." (PMID 37020597, 2023).
colorectal cancer (continued). "Taken together, we show that pKAL enhances the anticancer effect of β-Lap in HCT116-OxPt-R colorectal cancer cells through the modulation of TERT, CD44, and EGFR-mediated multiple signaling networks." (PMID 38139333, 2023). "In colorectal cancer, PTBP1 is often overexpressed which leads to the alternative splicing of CD44, promoting colorectal cancer progression." (PMID 36508323, 2023). "In colorectal cancer, CD133+/CD44+ colon cancer stem cells have a stronger capacity of bone marrow derived mesenchymal stem cells (BM-MSCs) recruitment compared with CD133-/CD44- colon cancer cells due to IL-8/CXCR2 chemotaxis." (PMID 37124519, 2023). "Taken together, our results show that pKAL enhances the anticancer effect of β-Lap in HCT116 colorectal cancer cells containing OxPt-R by downregulating TERT, CD44, EGFR, and upregulated oxaliplatin resistance-related proteins." (PMID 38139333, 2023). "We apply our novel scores to quantify the spatial expression of four different membrane markers, i.e., HER2, CMET, CD44, and EGFR in immunohistochemically (IHC) stained tissue sections of colorectal cancer patients." (PMID 36601480, 2022). "The viability, proliferation, stemness and migration of CD133+/CD44+, CD133−/CD44−, and colorectal cancer cells after transfection or the co-culture with exosomes were detected by MTT, colony formation, spheroid, and wound healing assays, respectively." (PMID 35470736, 2022). "Compared with colorectal cancer cells, the viability, proliferation, stemness, and migration of CD133+/CD44+ cancer cells were stronger, while these of CD133−/CD44− cancer cells were weaker." (PMID 35470736, 2022). "Adriamycin-treated colorectal cancer cell lines become senescent and upregulate expression of CD133 and CD44." (PMID 35844581, 2022). "In this study, we analyzed the protein and mRNA expression of BRG1 and CD44 and showed a positive correlation between BRG1 and CD44 expression in both colorectal cancer tissues and cell lines." (PMID 35590122, 2022). "We apply our novel scoring approaches to resections from a cohort of 34 colorectal cancer patients that have been stained by immunohistochemistry for HER2, CMET, CD44, and EGFR." (PMID 36601480, 2022). "Consistently, levels of prostaglandin E2 (PGE2), one of the members of the prostanoid, correlated with cancer stem cell markers in colorectal cancer, including CD133, CD44, LRG5, and SOX2." (PMID 36494785, 2022). "A few DEPs have been previously reported as molecules connected with response to RT in colorectal cancer, including FGB, CD44, GLUT1/SLC2A1, PON1." (PMID 35205741, 2022). "Activation of the Wnt/β-catenin signaling pathway drives colorectal cancer growth by deregulating the expression of many downstream targets, such as c-JUN, c-Myc, cyclin D1, CD44 and Axin2." (PMID 35065674, 2022). "During searching through different databases, we utilized multiple combinations of MeSH words “CD44,” “CD133,” “Colorectal cancer,” “Cancer stem cells,” “Treatment,” “prognosis,” and “Diagnosis”." (PMID 36415383, 2022). "Recently, in colorectal carcinoma, Ganesh et al37 have established a link between L1CAM and cancer stemness, where L1CAM characterizes a CD133/CD44 expressing stem‐like cells population endowed with enhanced tumorigenic potential and increased chemoresistance." (PMID 35429348, 2022). "A recent study reported that SOX2 expression primarily coincided with CD44+ and ALDH1+ population in pancreatic CSCs and CD44+ and CD24+ in colorectal cancer." (PMID 33445526, 2021). "; however, the expression of colorectal CSC markers such as CD44, CD133, and ALDH was similar to that of radiosensitive colorectal cancer cells under untreated conditions." (PMID 33445526, 2021). "This analysis showed that CD133, CD44, and SOX2 expression and ALDH activity were slightly increased in TCCM-treated colorectal cancer cells, whereas TCCM-DPA treated cancer cells exhibited a significant decrease in the expression/activity of these proteins." (PMID 34573091, 2021).